EGFR (epidermal growth factor receptor)
Diseases named in the same sentence as EGFR in open-access papers (continued):
Sharing a sentence is not in itself a finding about the gene and the disease.
hepatocellular carcinoma (continued). "Finally, the activation of the HRAS/PI3K/AKT pathway by EGFR-induced SOS1 also inhibits cisplatin-induced apoptosis, suggesting a common apoptosis-evasion mechanism in hepatoma cells." (PMID 25980493, 2015). "The EGFR signaling axis has been shown to play a key role during liver regeneration following acute and chronic liver damage, as well as in cirrhosis and hepatocellular carcinoma (HCC) highlighting the importance of the EGFR in the development of liver diseases." (PMID 26729094, 2015). "Inhibiting EGFR potentiates TGF-β-induced NOX4 up-regulation and increases hepatoma cell death." (PMID 23434665, 2013). "MUC15 was with decreased expression in hepatocellular carcinoma (HCC), and its overexpression significantly suppressed EGF induced dimerization of EGFR and activation of PI3K-AKT pathway, which finally inhibited tumor cell migration and invasion." (PMID 40225867, 2025). "The authors found that lnc-EGFR was highly expressed in Treg cells and positively correlated with FOXP3 expression in hepatocellular carcinoma (HCC)." (PMID 37189549, 2023). "Otherwise, in hepatocellular carcinoma (HCC), YTHDF2 acts as a tumor suppressor and promotes the degradation of epidermal growth factor receptor (EGFR) mRNA, and negatively modulates its stability." (PMID 35327559, 2022). "PGRMC1 has been reported to exist in co-precipitated protein complexes with epidermal growth factor receptor (EGFR), which is considered a useful therapeutic target in hepatocellular carcinoma (HCC)." (PMID 34069911, 2021). "Our collective findings suggest that sorafenib promotes YB-1 phosphorylation through effect from the EGFR/PI3K/AKT pathway, leading to significant enhancement of hepatocellular carcinoma (HCC) cell metastasis." (PMID 33379356, 2020). "In hepatocellular carcinoma, sex differences are also found in several signaling pathways that are targets for anti-cancer therapies: PPAR is enriched for genes overexpressed in females, while PI3K, PI3K/AKT, EGFR, IL-2 are enriched for genes overexpressed in males." (PMID 33330090, 2020). "Previous studies reported that silencing of GALNT2 could inhibit insulin-induced insulin receptor activation and Akt phosphorylation in hepatoma cells, whereas overexpression of GALNT2 in oral cancer cells could promote EGF-induced phosphorylation of EGFR and Akt." (PMID 32559179, 2020). "However, those anti-EGFR agents have not been proved positive evaluation in hepatocellular carcinoma (HCC) despite the expression of EGFR is commonly high." (PMID 32079107, 2020). "Experiments were performed using three hepatocellular carcinoma (HCC) cell lines, Hep3B, HepG2 and PLC/PRF/5, expressing various levels of EGFR, ErbB2 and ErbB3." (PMID 32515546, 2020). "In addition to directly interacting with the ABCB1 3′-UTR, miR-338-5p could target the EGFR/ERK1/2 pathway to inhibit the expression of ABCB1, resulting in increased sensitivity of hepatoma cells to DOX." (PMID 29527329, 2018). "Inhibition of EGFR signaling delayed but did not block liver regeneration in different experimental models and EGFR inhibitors showed lack of clinical efficacy in human hepatocellular carcinomas." (PMID 28445529, 2017). "Similarly, analysis of sequencing data from hepatocellular carcinoma (HCC) patients suggested the pivotal role of gene body hypermethylation-activated EMX1-FL (the full-length protein isoform of EMX1) in promoting tumorigenesis and metastasis through EGFR-ERK signaling pathway." (PMID 40517231, 2025). "For example, in hepatocellular carcinoma (HCC), the recognition protein YTHDF2 directly recognises and binds to the m6A modification site of epidermal growth factor receptor (EGFR), destabilising and degrading it, thereby inhibiting cell proliferation and growth." (PMID 38572667, 2024).
hepatocellular carcinoma (continued). "The upregulation of miR-490 expression levels in MC-derived exosomes stimulated by HCV-E2 and transferred to hepatocellular carcinoma (HCC) cells inhibit tumor metastasis by reducing the activity of the EGFR/AKT/ERK1/2 pathway, thereby suppressing invasion of HCC cells." (PMID 35242126, 2022). "The results of Bertozzi group showed that the EGFR and HER2 could be degraded by GalNAc-LYTACs in hepatocellular carcinoma (HCC) cells." (PMID 35813205, 2022). "Moreover, lnc-EGFR has also been shown to stimulate Treg differentiation, inhibit CTL activity, and promote hepatocellular carcinoma (HCC) growth." (PMID 34295338, 2021). "Interestingly, previous works have shown that the ectopic expression of cell surface B4GALT1 promotes apoptosis in human hepatocellular carcinoma cells inhibiting EGFR dimerization and tyrosine phosphorylation, indicating that B4GALT1 may be an inhibitor of EGFR signaling." (PMID 31635093, 2019). "In hepatocellular carcinoma (HCC), LPS promotes cell survival, proliferation, invasion, and production of pro-inflammatory mediators, including TNF-α, iNOS, IL-1β, IL-6, CCL-2, CCL-22, vimentin, and epidermal growth factor receptor (EGFR), through the induction of TLR4 signaling." (PMID 40444051, 2025). "MS VLPs delivered long non-coding RNA maternally expressed gene 3 (MEG3) specifically to epidermal growth factor receptor (EGFR)-positive hepatocellular carcinoma (HCC) cell lines, without activating EGFR downstream signaling pathways." (PMID 39337427, 2024). "ADAM17, a known ectodomain sheddase of epidermal growth factor receptor (EGFR) ligands such as heparin-binding epidermal growth factor-like growth factor (HB-EGF), has been reported to enhance actin cytoskeletal remodelling at the tip of the lamellipodium in hepatocellular carcinoma (HCC) cells." (PMID 37492637, 2023). "A study showed that miR-486-3p can adjust the sorafenib response in hepatocellular carcinoma (HCC), targeting both fibroblast growth factor receptor 4 (FGFR4) and epidermal growth factor (EGFR), and adjusts it to be a better treatment target than FGFR4 and EGFR inhibitors." (PMID 35215154, 2022). "The precise role of Epidermal Growth Factor Receptor (EGFR) in Hepatocellular carcinoma (HCC) cells is unknown and EGFR inhibitors have not achieved positive clinical results." (PMID 32079107, 2020). "Further, atezolizumab plus bevacizumab is the standard of care for patients with unresectable hepatocellular carcinoma, and atezolizumab plus bevacizumab in combination with chemotherapy is approved for patients with metastatic non-squamous NSCLC and no EGFR or ALK alterations." (PMID 34940094, 2021). "This might rely on the fact that alterations in EGFR are pivotal and very frequent in primary human GBM but not hepatoma." (PMID 24243798, 2013).
triple-negative breast carcinoma (478 papers, 2007 to 2026). An invasive breast carcinoma which is negative for expression of estrogen receptor (ER), progesterone receptor (PR), and human epidermal growth factor receptor 2 (HER2). "(2011) reported EGFR mutations, specifically exon 19 deletions and exon 21 missense (L858R) mutations, in 11.8% of Triple Negative Breast Cancer (TNBC) samples analysed." (PMID 41552637, 2026). "IL-22 enhances migration and maintains stemness in cancer cells across multiple cancer types, and IL-26 has been linked to EGFR-TKI resistance in triple-negative breast cancer." (PMID 40452847, 2025). "EGFR is often expressed in basal triple negative breast cancer (TNBC), and is associated with tumor size, poor differentiation, worse relapse-free and overall survival, and shorter metastasis free survival." (PMID 40501689, 2025). "Cancer cells with genetic mutations or receptor heterogeneity, such as those in triple-negative breast cancer, exhibit resistance to EGFR inhibitors." (PMID 41140511, 2025). "Epidermal growth factor receptor (EGFR) pathway activation causes chemotherapy resistance, and inhibition of the EGFR pathway sensitizes triple-negative breast cancer (TNBC) cells to chemotherapy in preclinical models." (PMID 39356138, 2024). "The epidermal growth factor receptor (EGFR) pathway has been implicated as a driver of chemotherapy resistance in triple-negative breast cancer (TNBC)." (PMID 39356138, 2024). "Src is emerging as a promising target in triple-negative breast cancer (TNBC) treatment because it activates survival signaling linked to the epidermal growth factor receptor." (PMID 37686097, 2023). "In particular, EGFR has been frequently overexpressed and associated with a poor prognosis in triple-negative breast cancer." (PMID 38203378, 2023). "Somatic EGFR T790M mutations have been reported in a limited population of patients with triple-negative breast cancer." (PMID 37265791, 2023). "It was reported that knockdown of SPRY1 can reduce the risk of distant metastasis from triple negative breast cancer via inhibiting EGF/EGFR mediated pathways." (PMID 36035369, 2022). "Some studies have suggested that the expression of epidermal growth factor (EGFR) is relatively high in triple negative breast cancer and it is the main cause growth." (PMID 33934088, 2021). "EGFR is overexpressed or amplified in 45–70% of triple-negative breast cancer (TNBC) and is associated with an aggressive disease phenotype." (PMID 33663560, 2021). "Another receptor frequently overexpressed in triple-negative breast cancers (TNBCs), a subgroup associated with particularly poor treatment response and outcomes, is the epidermal growth factor receptor (EGFR)." (PMID 31532771, 2019). "As triple negative breast cancers (TNBC) have been found to harbour mutations in EGFR, we wished to determine how they affect a relatively normal breast cell line." (PMID 25969993, 2015). "We read with interest the study by Teng and colleagues reporting a high frequency (11.4 %) of epidermal growth factor receptor (EGFR)-activating mutations in triple-negative breast cancer (TNBC) in a Singapore cohort." (PMID 26290189, 2015). "Epidermal growth factor receptor (EGFR) is frequently overexpressed in aggressive such as triple-negative breast cancer and associated with poor clinical outcomes." (PMID 26025929, 2015). "Activation of src is associated with the activation of EGFR pathway which is frequently expressed in triple negative breast cancers." (PMID 29147345, 2013). "These tumors were also associated with high EGFR expression, which is associated with worse prognosis for basal/triple-negative breast cancers." (PMID 22662240, 2012). "Two studies recently reported around 10% of EGFR activating mutations in triple negative breast cancers from Asian patients." (PMID 22293080, 2012).
triple-negative breast carcinoma (continued). "In this study, we report the presence of EGFR mutations, notably exon 19 deletions and exon 21 missense (L858R) mutations, in 11.8% of triple negative breast cancers evaluated." (PMID 21457545, 2011). "More complete sampling of EGFR mutation status in triple negative breast cancer is needed to determine the true mutation rate." (PMID 21457545, 2011). "This study demonstrated existing EGFR mutations in a relatively small study size of 70 triple negative breast cancers in a Singapore population (8 of 70 samples)." (PMID 21457545, 2011). "This study is among the first to document the presence and estimate the prevalence of EGFR mutations in triple negative breast cancer." (PMID 21457545, 2011). "Consequently, the simultaneous overexpression of c-MET and EGFR in triple-negative breast cancer (TNBC) is associated with poorer clinicopathological outcomes and increased risks." (PMID 41234389, 2025). "Aberrant EGFR expression is associated with triple-negative breast cancer (TNBC)." (PMID 37095176, 2023). "Similarly, in triple-negative breast cancer patients, an association between syndecan-1 and EGFR overexpression has been found." (PMID 34680238, 2021). "Expression of EGFR has been linked to prognosis in basal/triple-negative breast cancer." (PMID 22662240, 2012). "We, therefore, sought to characterize EGFR mutations in triple negative breast cancers." (PMID 21457545, 2011). "We sought to determine whether such mutations exist in triple negative breast cancers, the results of which may help to select patients suitable for inclusion in clinical trials evaluating the role of anti-EGFR directed therapies in this condition." (PMID 21457545, 2011). "In addition, increased expression and/or gene amplification of EGFR have been observed in many human cancers, including triple negative breast cancer MDA-MB-231 cells, and has been associated to increased cell proliferation and motility, disease progression and poor prognosis." (PMID 33633298, 2021). "However, EGFR missense mutations identified in the BRCA1/2 tumours were different from those encountered in our triple negative breast cancer study, possibly due to different patient selection where the BRCA1/2 linkage of our study cohort is unknown." (PMID 21457545, 2011). "AXL has also been identified as a predictive marker of resistance to EGFR-targeted drugs in triple-negative breast cancer (TNBC) cell lines." (PMID 40560045, 2025). "For instance, CAP induced the apoptosis of triple negative breast cancer (TNBC) cells via activating EGFR(Y992/1173), and triggered TNBC ferroptosis via stimulating EGFR(Y1068) phosphorylation." (PMID 40989573, 2025). "In basal-like/triple negative breast cancer cells, β-catenin maintains the stability of epidermal growth factor receptor (EGFR)-governed genes, including interleukin-6 (IL-6)." (PMID 40562819, 2025). "The anti-EGFR nanobody 7D12 conjugation refined the cellular absorption and cytotoxicity of the micelles based on quantum dots in EGFR-overexpressing MDA-MB-468 triple-negative breast cancer (TNBC) cells." (PMID 41304734, 2025). "And digestive tumor research can reference its mechanisms elsewhere, e.g., metastasis inhibition via circNAV3/miR-4262/ST6GALNAC5/EGFR (as in triple-negative breast cancer) or progression suppression through m6A/IGF2BP3-stabilized TWIST1 mRNA." (PMID 40978472, 2025). "We serum-starved U-2 OS (osteosarcoma) and BT20 (EGFR-amplified triple-negative breast cancer) cells and exposed them to various RTK ligands (EGF, FGF1, PDGF)." (PMID 40667115, 2025). "HUNK is implicated in tumorigenesis, metastasis, and invasion via epidermal growth factor receptor activation in HER2-positive and triple-negative breast cancers." (PMID 41487817, 2025). "Overexpression of EGFR is more common in triple-negative breast cancer (TNBC) compared to other subtypes, and tamoxifen’s efficacy can depend on HER2 status." (PMID 40417193, 2025).
triple-negative breast carcinoma (continued). "In previous studies using immunohistochemistry (IHC), EGFR was found to be overexpressed in a subgroup of triple-negative breast cancer (TNBC) patients." (PMID 41188939, 2025). "This research integrated essential tumor microenvironment components with cancer cell molecules to explore the invasion mechanism in triple-negative breast cancer and assess the prognostic value of the EGFR and collagen IV ratio." (PMID 38730959, 2024). "The triple-negative breast cancer MDA-MB-231 cells expressing both EGFR and PD-L1 were co-cultured for 48 h at two different effector/target ratios (1:1 and 2:1) with anti-CD3-prestimulated PBMCs expressing PD-1 and 4-1BB." (PMID 38804302, 2024). "A proliferative role for IGFBP-3 is observed in triple-negative breast cancer (TNBC) cells via modulating sphingosine kinase-1 (SphK1) localization to activate EGFR signaling." (PMID 39619437, 2024). "For instance, circHER2 encodes a novel protein, HER2-103aa, which forms a dimer with EGFR to phosphorylate AKT (Thr308) in certain triple-negative breast cancers (TNBCs)." (PMID 38360682, 2024). "The incorporation of the anti-EGFR nanobody significantly improved cellular uptake and cytotoxicity in EGFR-overexpressing triple-negative breast cancer cells, enhancing tumor targeting and treatment efficacy in an orthotopic xenograft model." (PMID 38730959, 2024). "Cell context–dependent, however, a hypoxia-mediated EGFR downregulation has been reported likewise including experiments with the poorly differentiated triple-negative breast cancer cell line MDA-MB-231 that was also used in the present study." (PMID 38294517, 2024). "We show that brain endothelial cells activate EGFR signalling in triple-negative breast cancer cells with propensity to metastasise to the brain." (PMID 38762624, 2024). "Most primary Triple Negative Breast Cancers (TNBCs) show amplification of the Epidermal Growth Factor Receptor (EGFR) gene, leading to increased protein expression." (PMID 38605363, 2024). "TINAGL1 was defined as a competitive inhibitor for fibronectin-induced activation of FAK or EGFR, and consequently suppressed tumor progression in mouse models with triple-negative breast cancer." (PMID 38355577, 2024). "Recently our colleagues described a peptide therapeutic that kills epidermal growth factor receptor (EGFR)-dependent triple negative breast cancer cells (TNBC) in vitro and in mouse models." (PMID 38909779, 2024). "Prior work identified a cell-permeable peptide termed SNX1.3, derived from the BAR domain of sorting nexin 1 (SNX1), that potently blocks the retrograde and nuclear trafficking of EGFR in triple negative breast cancer cells." (PMID 38909779, 2024). "In contrast, IGFBP-3 stimulates proliferation in triple-negative breast cancer (TNBC) cells via EGFR activation." (PMID 39619437, 2024). "We demonstrated the exceptional contrast efficiency and high photothermal activity of the anti-EGFR-MPB nanocomposite in mouse models with triple-negative breast cancer." (PMID 39525484, 2024). "For example, combining anti-CD3 and anti-epidermal growth factor receptor (EGFR) antibodies with the PDGFR region on EV membranes can simultaneously target T cells and EGFR-expressing triple-negative breast cancer cells." (PMID 39802949, 2024). "NO has also been shown to rapidly induce EGFR Y1045, Y1068, and Y1173 phosphorylation in triple-negative breast cancer cells." (PMID 38601214, 2024). "What is more, the anti-EGFR monoclonal antibody (clone LA1) blocking EGFR has been shown to effectively inhibit in vitro the CD44-mediated aggregation of triple-negative breast cancer cells, reducing metastasis." (PMID 38427120, 2024). "The in situ molecular imaging and quantitative analysis of EGFR and collagen IV were performed in triple-negative breast cancer using quantum dot-based technology." (PMID 38730959, 2024).